EGFR (epidermal growth factor receptor)
Diseases named in the same sentence as EGFR in open-access papers (continued):
Sharing a sentence is not in itself a finding about the gene and the disease.
lung cancer (continued). "Recently, target therapy alone or combined with chemotherapy has been used to treat advanced NSCLC, and drugs targeting the EGFR and VEGF pathways have become new therapeutic options for lung cancer therapy." (PMID 29121075, 2017). "Fortunately, over past decades, the finding of some driver genes in NSCLC, such as epidermal growth factor receptor (EGFR), anaplastic lymphoma kinase (ALK) and kirsten rat sarcoma viral oncogene homolog (KRAS), was a major breakthrough in lung cancer field." (PMID 28423587, 2017). "These independent lines of data indicated that miR-370 attenuated the EGFR-related ERK1/2 and AKT signaling in lung cancer cells in vitro." (PMID 29152147, 2017). "Our study supports the functional interaction between the EGFR and PKC pathways in lung cancer and provides a clinically exploitable strategy for erlotinib-less sensitive non-small cell lung cancer patients." (PMID 28399187, 2017). "CI-988 inhibited the abilities of CCK-8 to elevate cytosolic Ca2+, to stimulate EGFR, ERK and FAK tyrosine phosphorylation as well as VEGF expression, and so cell growth and proliferation in NCI-H727 lung cancer cells." (PMID 29262666, 2017). "Ourstudy demonstrates that EGFR stabilizes SCD1 through Y55 phosphorylation, thereby up-regulating MUFA synthesis to promote lung cancer growth." (PMID 28724430, 2017). "Our data support that, together with other oncogenes such as Kras or EGFR, USP24 downregulation positively affected the efficacy of lung cancer formation." (PMID 27991932, 2017). "The lung cancer patients with EGFR mutant type were treated with EGFR TKI agents and those with EGFR wildtype subgroup were treated with chemotherapy based on guideline recommendations." (PMID 29100283, 2017). "Hyper-activation of the EGFR-Ras-MAPK pathway, where mutant proteins are involved, is the most common alteration in lung cancer." (PMID 29285267, 2017). "In this study, we find that EGFR stabilizes SCD1 through Y55 phosphorylationto increase intracellular MUFA level and consequently promotes lung cancer growth." (PMID 28724430, 2017). "For instance, epidermal growth factor (EGF)/epidermal growth factor receptor (EGFR) has been reported to be responsible for elevated claudin-2 expression in CRC and lung cancer." (PMID 28383479, 2017). "The epidermal growth factor receptor (EGFR) and anaplastic lymphoma kinase (ALK) genes are the most important drivers in lung cancer." (PMID 29167003, 2017). "In this study, we found that the 3′UTR of the EGFR contained a potential binding site of miR-370 and the levels of EGFR were negatively associated with the levels of miR-370 expression in several human lung cancer cell lines and non-tumor bronchial epithelial cells." (PMID 29152147, 2017). "In this study, we developed a novel EGFR-TKI inhibitor (cAMP-H3BO3 complex), which significantly inhibits EGFR auto-phosphorylation and induces lung cancer cell apoptosis." (PMID 28915593, 2017). "Various receptors, including folate receptor alpha (FRA), epidermal growth factor receptor (EGFR), integrins, CD44, and transferrin, are known to be overexpressed in lung cancer cells." (PMID 28290155, 2017). "Loss of KEAP1, a negative regulator of NFE2L2/NRF2, modulated the response to BRAF, MEK, EGFR, and ALK inhibition in BRAF-, NRAS-, KRAS-, EGFR-, and ALK-mutant lung cancer cells." (PMID 28145866, 2017). "In the literature, studies on clonal changes between primary tumors and metastatic lesions in EGFR in OSCC were few and most related studies focused on lung cancer." (PMID 28854970, 2017). "Furthermore, all patients were postoperative patients with lung cancer who received a EGFR mutation test, and our study population may not represent the general population." (PMID 29110716, 2017).
lung cancer (continued). "To prospectively identify mechanisms of resistance to EGFR, ALK, BRAF, and MEK inhibition in lung cancer, we performed CRISPR-Cas9 drug resistance screens in five cancer cell lines with different alterations in the RTK/Ras/MAPK pathway." (PMID 28145866, 2017). "To further confirm this result, we treated the lung cancer cell line (A549) with cAMP-H3BO3 complex and found that the phosphorylation of EGFR was significantly decreased compared to that achieved with cAMP alone." (PMID 28915593, 2017). "To date, our study has the largest case number to show that the combination of statins with EGFR-TKIs prolongs PFS and OS in patients with lung cancer." (PMID 28158206, 2017). "Targeting epidermal growth factor receptor (EGFR) and downstream signaling transduction has been shown to be beneficial in the treatment of lung cancer, which accounts for 19.4% of all cancer-related deaths worldwide." (PMID 27935868, 2017). "The developments of platinum-based chemotherapy and targeted therapies for EGFR-sensitive and ALK-positive patients have been regarded as milestones for lung cancer treatment." (PMID 29137407, 2017). "Erlotinib is an EGFR tyrosine kinase inhibitor (TKI), which is widely used in clinical studies, and its therapeutic effect has been confirmed in a specific cohort of lung cancer subjects." (PMID 28399187, 2017). "A number of established lung cancer oncogenes have also been included in the classifier, such as IL1R2, JUNB, EGFR, SOX9, FOSB, and JUND." (PMID 27935865, 2017). "Our previous study showed that the downregulation of fucosyltransferase IV (FUT4) expression inhibited the biosynthesis of Lewis Y antigen (LeY), which inactivated EGFR and downstream signaling pathways to ultimately decrease EMT in lung cancer cells." (PMID 28798691, 2017). "BA1 increased tyrosine phosphorylation of the EGFR and ERK in lung cancer cells, which was blocked by AM-37 and ST-36." (PMID 28785244, 2017). "NF-κB has been identified as a critical mediator of EMT in cancer progression and IGF1R pathway has been reported to be involved in EGFR TKI resistance and induction of EMT in lung cancer." (PMID 29190911, 2017). "In the present study, VJ, a small molecule, simultaneously inhibited EGFR, AKT, mTOR activation, and effectively suppressed cell proliferation and promoted induction of apoptosis in lung cancer cells, expressing wild-type EGFR." (PMID 29234489, 2017). "Engagement of the EGFR by its ligand can activate the downstream MAPK and AKT signaling to promote the proliferation, angiogenesis and metastasis of lung cancers." (PMID 29152147, 2017). "Given the importance of EGFR activation in NSCLC pathogenesis, we investigated the effect of sialidase NEU3 overexpression on EGFR downstream pathway activation and TKI targeted therapies sensitivity in a series of lung cancer cell lines." (PMID 29088281, 2017). "Among the different forms of lung cancer, non-small-cell lung cancer (NSCLC) is treated with an epidermal growth factor receptor (EGFR) tyrosine kinase inhibitor, such as gefitinib." (PMID 28225782, 2017). "The previous evidence has confirmed the potential regulation role of TGFB on these genes, such as EGR1, EGFR, and IL6 in the lung cancer." (PMID 28959347, 2017). "Lung cancer stem cells have elevated aldehyde dehydrogenase (ALDH) activity and erlotinib increased the ALDH stem-like cells in EGFR mutant cancer cells." (PMID 28521301, 2017). "However, the two available lung cancer cell lines with EGFR mutations in our lab could not form tumor spheres and thus could not be tested in this study." (PMID 28854941, 2017). "Interestingly in lung cancer cells which harbor an activating mutation in EGFR (HCC827) we observed that high percentage of the LysRS are phosphorylated at position s207, implying that at least in vitro, aberrant activation of EGFR can lead to over-activation of the LysRS pathway." (PMID 29029422, 2017).
lung cancer (continued). "Several 3rd-generation EGFR TKIs [e.g., AZD9291 (osimertinib), CO1686, and olmutinib have been developed to overcome TKI resistance in lung cancer that have shown promising effects." (PMID 28422737, 2017). "A positive clinical correlation among EGFR activation, SCD1 Y55 phosphorylation, SCD1 protein expression and poor patient prognosis in lung cancer further strengthens the importance of our findings." (PMID 28724430, 2017). "The developments of platinum-based chemotherapy and targeted therapies for EGFR-sensitive and ALK-positive patients have been milestones in lung cancer treatment." (PMID 27713133, 2017). "Furthermore, survival curve analysis of all INCAN lung carcinoma patients with EGFR-non-mutated status identified a better overall survival index (statistically significant at p≤0.005) with lower MEOX2 and GLI-1 protein expression levels (p=0.122 and p=0.002, respectively)." (PMID 28978016, 2017). "As we had proven that MIIP decreases EGFR/Ras/MEK/ERK pathway activation via decrease of EGFR protein expression, we tested the growth of MIIP-overexpressing or knockdown lung cancer cells." (PMID 26824318, 2016). "This leads to the downregulation of steady-state EGFR and less activation of EGFR and downstream Ras/MEK/ERK pathway, which inhibits lung cancer cell proliferation." (PMID 26824318, 2016). "Preclinical studies showed enhanced radiation response with dual HER3/EGFR inhibition in SCCHN and lung cancer model systems." (PMID 27843803, 2016). "Here we summarized the signaling pathways involved in EGFR-TKI induced autophagy, and reviewed the roles of autophagy in the treatment and chemoresistance of EGFR-TKI treatment in lung cancer." (PMID 27666552, 2016). "We first investigated the EGFR signal transduction pathways upon gefitinib treatment in both HCC827 and H3255 lung cancer cells." (PMID 27419630, 2016). "Molecular alterations in EGFR, KRAS, and ALK genes are involved in lung cancer pathogenesis, but clinical use of these biomarkers is still a debatable issue." (PMID 27863408, 2016). "In the current study, we have exploited the interconnected relationship between the EGF/EGFR axis with the induction of EMT20 and the ability of erlotinib to modulate the phenotype of lung cancer cell lines towards a more epithelial one." (PMID 27685624, 2016). "In a previous study, receptor tyrosine kinase-like orphan receptor 1 (ROR1) bound to EGFR led to activation of the phosphatidylinositol 3 kinase (PI3K) pathway, which is critical in lung cancer." (PMID 26945426, 2016). "Lately, various therapies such as combination chemotherapy, EGFR tyrosine kinase inhibitors (EGFR-TKI), and angiogenesis inhibitors have become available for brain metastasis originating from lung cancer." (PMID 26801624, 2016). "Their study results showed that male patients with history of pulmonary TB had a poor EGFR-TKI response and 1-year progression-free survival of lung cancer." (PMID 26962806, 2016). "Epidermal growth factor receptor-tyrosine kinase inhibitors (EGFR-TKIs) and anaplastic lymphoma kinase (ALK) inhibitors have dramatically changed the strategy of medical treatment of lung cancer." (PMID 27070423, 2016). "This study aimed to elucidate the association of the content of mutant epidermal growth factor receptor (EGFR) deoxyribonucleic acid (DNA) with the treatment response to EGFR-tyrosine kinase inhibitor (TKI) and survival in patients with lung cancer." (PMID 27368002, 2016). "Cetuximab (Erbitux, C225), monoclonal antibody to epidermal growth factor receptor (EGFR) is used as one of anti-EGFR agents for the treatment of metastatic colon and lung cancer." (PMID 26751081, 2016).
lung cancer (continued). "To determine if VDR protein is present in EGFR mutant NSCLC, we utilized a lung cancer tissue microarray (TMA) constructed within the Pathology Resource Network at Roswell Park Cancer Institute." (PMID 26654942, 2016). "The development of molecular targeted anticancer agents has resulted in better therapeutic responses in some types of lung cancer, including non-small cell lung cancer (NSCLC) with mutant epidermal growth factor receptor (EGFR)." (PMID 27708216, 2016). "Our results show that scFv-9R/HER2si complex, through binding to EGFR homodimers or EGFR/HER2 heterodimers, internalize into EGFR-positive lung cancer cells and release HER2si, consequently leading to HER2 silence." (PMID 26988752, 2016). "Scutellarein which is botanical extract bezielle inhibited the proliferation of human lung cancer through ERK and NF-κB mediated by EGFR." (PMID 26636541, 2016). "When combined with cetuximab that blocks EGFR dimerization, EAI045 markedly reduced tumor growth in a mouse model of L858R/T790M—mutant-driven lung cancer." (PMID 27448564, 2016). "For instance, EGFR and ALK have been identified as key biomarkers in lung cancer, and molecular tests for EGFR and ALK have become common in lung cancer treatment." (PMID 27589834, 2016). "In this study, we attempted to determine the content of mutant EGFR DNA in lung cancer cells and NSCLC tissues using the Therascreen EGFR RGQ PCR kit (Qiagen, Hilden, Germany)." (PMID 27368002, 2016). "Various carcinogens induce EGFR/RAS/MAPK signaling, which is critical in the development of lung cancer." (PMID 27167001, 2016). "Taken together, these results suggest that down-regulating FUT4 expression decreased LeY biosynthesis which leads to the inhibition of EGFR activation, the downstream MAPK and NF-κB signal pathways in lung cancer cells." (PMID 26636541, 2016). "Second-generation irreversible EGFR TKI, afatinib, had also been approved for treating EGFR mutant lung cancer patients, but the mechanism of acquired resistance to afatinib has not been well studied." (PMID 26862733, 2016). "Previous studies identified three major genes (EGFR, KRAS, and ALK) for the development of lung cancer." (PMID 27863408, 2016). "After inhibition of the phosphorylation of EGFR, downregulation of CDH5 protein was observed in the lung cancer cells studied." (PMID 27362942, 2016). "We were particularly interested in the performance of EGFR testing in our NGS assay, because mutations in this gene may be therapeutically targetable, and because it is often challenging to analyze, as DNA degradation and low tumor percentage are frequently encountered in lung cancer specimens." (PMID 27043212, 2016). "The 3rd generation EGFR-TKI, AZD9291, is regarded as a breakthrough in the treatment of gefitinib- or erlotinib-resistant lung cancers." (PMID 27825114, 2016). "We also demonstrated that ZEB1 upregulation was observed in additional NSCLC cell lines and human samples with EMT-related EGFR-TKI resistance, suggesting that ZEB1 is a possible target to overcome this kind of resistance in clinical lung cancer." (PMID 26789630, 2016). "For example, amplifications of EGFR in gliomas, MYCN in neuroblastoma, MYC in acute myeloid leukemia, and ERBB2 in breast, ovarian, and lung cancers have been reported." (PMID 26755558, 2016). "Undoubtedly, tyrosine kinase inhibitors (TKI) for EGFR and ALK are currently the standard of care for EGFR-mutant and ALK-rearranged lung cancer patients, respectively." (PMID 26992220, 2016). "Afatinib, an EGFR-TKI inhibitor, was used to inhibit the phosphorylation of EGFR in PC9 and H1975 lung cancer cells." (PMID 27362942, 2016).
lung cancer (continued). "On the one hand, ginsenoside Rg3 inhibits lung cancer migration and invasion by down-regulating fucosyltransferase IV (FUT4)-mediated EGFR inactivation and blocking MAPK and NF-κB signaling pathways." (PMID 27655708, 2016). "Targeting oncogenic drivers, such as epidermal growth factor receptor (EGFR) and anaplastic lymphoma kinase (ALK), has brought the most encouraging improvements in lung cancer treatment." (PMID 26919104, 2016). "Resistance to EGFR inhibitors reportedly involves activation of signal transducer and activator of transcription 3 (STAT3) in glioma and lung cancer." (PMID 26542452, 2015). "Recently, an oncogenic mechanism of EGFR-MEK-ERK-MMP was reported, which contributed to lung cancer invasion." (PMID 26304749, 2015). "Recently, several third-generation, irreversible, selective EGFR inhibitors such as AZD9291 and CO1686 have shown promise in pre-clinical studies and provided hope for patients with advanced lung cancers that have become resistant to gefitinib or erlotinib." (PMID 25674538, 2015). "Restoration of miR-145-5p expression using either vorinostat or 5-azacytidine, which released methylation of the miR-145 locus, led to inhibition of migration of lung cancer cells and to down-regulation of OCT-4, MYC, EGFR, MUC-1 and TPD52 expression." (PMID 26440147, 2015). "This indicates that the cross-talk between EGFR (and most likely its downstream substrates, which include RAS) and the ER modulates the progression and response to therapy of this subtype of lung cancer." (PMID 26468985, 2015). "Our panel included 22 genes, although the approved predictive biomarkers in colon and lung cancer are quite few (KRAS, NRAS, EGFR, ALK)." (PMID 25637035, 2015). "Aberrant activity or overexpression of epidermal growth factor receptor (EGFR) plays a critical role in NSCLCs, and targeting EGFR is a breakthrough in lung cancer treatment." (PMID 26593208, 2015). "Amplification of EGFR SCNA was reported in colorectal cancer, esophageal cancer, glioblastomas, lung cancer, salivary gland cancer, and osteosarcoma; taken together, these findings indicated that SCNA of EGFR is relatively common in cancer tissue." (PMID 25658832, 2015). "In addition, a higher percentage of EGFR-mutated cancers are observed in Asians patients than in the general U.S. population, which correlates with the higher percentage of never smokers among lung cancer patients in Asian countries." (PMID 26582178, 2015). "Mutations or abnormal expression of a number of molecules, including EGFR, KRAS, TITF1, B7-H1, and epigenetic regulators, are correlated with initiation and development of lung cancers." (PMID 26056041, 2015). "Guidance concerning tyrosine kinase inhibitors (TKIs) for patients with wild type epidermal growth factor receptor (EGFR) and advanced non–small-cell lung cancer (NSCLC) after first-line treatment is unclear." (PMID 25547901, 2015). "It has recently been reported that FAM83B can act as an important intermediary in aberrant EGFR/RAS signaling, and is actually highly expressed in several cancer tissues, such as breast and lung cancer." (PMID 25586059, 2015). "Specifically in lung cancer, STAT3 has been shown to function as one of the main downstream transcription factors in EGFR mutant ACs13 and to act as an oncogene in a chemically induced mouse model of lung cancer." (PMID 25734337, 2015). "It is well known that epidermal growth factor receptor (EGFR) is critical factor for the growth and metastasis of human lung cancer cells." (PMID 26516313, 2015). "The results indicated that the phosphorylation of Src Y418, EGFR Y1068 and STAT3 Y705 was reduced in a dose-dependent manner (50–500 nM) by digoxin in the A549 lung cancer cell line that possesses wild-type EGFR." (PMID 25955608, 2015). "EGFR is overexpressed in 43-89% of non–small-cell lung carcinoma (NSCLC) cells and has become an important therapeutic target for the treatment of lung cancer." (PMID 25915533, 2015).